CD4 (CD4 molecule)
Diseases named in the same sentence as CD4 in open-access papers (continued):
Sharing a sentence is not in itself a finding about the gene and the disease.
tumor (continued). "The exact role of CD4+ versus CD8+ T cells in antitumor immunity is likely to be dependent on the vaccination strategy and the tumor model to be engaged." (PMID 23071764, 2012). "This inhibition depends on CD4+ and CD8+ T cells in case of local tumor control and NK cell activity and IFN-γ in case of metastatic control." (PMID 22333315, 2012). "Although cytotoxic CD4+ and CD8+ T cells appear to mediate tumor killing using the same effector molecules, such as granzyme B and perforin, they target MHC-II and MHC-I-restricted antigens, respectively." (PMID 22400040, 2012). "As a further test of the importance of CD8-dependent CTL-mediated anti-tumor effects, CD4+ or CD8+ T lymphocytes were depleted in vivo using anti-CD4 or anti-CD8 monoclonal antibodies." (PMID 22860107, 2012). "One week after L19mTNFα/melphalan treatment a remarkable increase in the number of CD4+ and CD8+ T cells infiltrating the tumor was observed as compared to tumors from untreated animals." (PMID 22849661, 2012). "The premise of therapeutic cancer vaccine is that tumor-reactive T cells (including CD8+ and CD4+ T cells) can be induced and expanded in patients by exposing the host immune system to tumor-associated antigens (TAAs)." (PMID 22778760, 2012). "The B, CD3 T, CD4 T, CD 8 T and NK cell portion of CCR5−/− mice tumor tissue were 7.2%, 48.2%, 16.9%, 32.1% and 7.8%, respectively, compared to 2.9%, 11.1%, 2.3%, 0.6% and 3.1% of CCR5+/+ mice." (PMID 22567084, 2012). "Considering the important role of CD4+ in tumor immunotherapy, an IL-2 ELISPOT assay was employed to examine the CD4+ T cell response triggered by this immunization strategy." (PMID 23139820, 2012). "Overinduced CD4+CD25+high regulatory T cells (Treg) and downregulated NK cells contribute to tumor-relevant immune tolerance and interfere with tumor immunity." (PMID 22722448, 2012). "Cx mice also exhibited an increase in activated (CD25+CD69+) CD4+ and CD8+ T cells in the inguinal lymph node draining the tumour site." (PMID 22880080, 2012). "The efficacy of dual anti-OX40/IL-2c therapy required the presence of effector CD4 and CD8 T cells in the tumor-bearing host as depletion of either or both subsets abrogated its effects." (PMID 22496812, 2012). "TMZ chemotherapy also increased cross-priming of tumor antigen-specific CD4+ and CD8+ T cells in an animal model and suppressed Treg activation when TMZ-treated animals were vaccinated with tumor-antigen pulsed DCs." (PMID 23133490, 2012). "Together these data reveal that in our model, where CD4 T cells are present at the time of priming, CD8 T cells do not require additional signals from CD4 T cells to gain access to the tumor." (PMID 22911764, 2012). "BiTE antibodies activate both CD4+ and CD8+ T cell subsets; both subsets of T cells contribute to tumor cell killing at relatively low effector T cell:target tumor cell (E:T) ratios." (PMID 22574157, 2012). "Both CD4+ and CD8+ T cell counts of always were the highest among the three mirtazapine-treated, tumor-bearing animal groups." (PMID 22808019, 2012). "Several vaccination strategies used against breast cancer have been successfully employed to induce tumor-specific CD8+ and CD4+ T-cell responses; however, such immunological responses have rarely been potent enough to achieve objective results." (PMID 23097673, 2012). "Taken together, we observed an increase of activated CD4+ and CD8+ lymphocytes in spleens and lymph nodes of tumor-bearing animals compared to tumor-free LLA-TG-3 mice." (PMID 22674057, 2012). "By taking advantage of a comprehensive clinical follow-up database, numbers of CD4+, FOXP3+ and IL-17+ TILs and their occurrence in different tumor compartments was correlated with clinico-pathological features and survival data." (PMID 22471961, 2012). "A population of spleenic CD4+CD69+, but CD25− and FoxP3−, T cells with regulatory activity has been described in tumor-bearing mice." (PMID 22319577, 2012).
tumor (continued). "We found that both CD4+ and CD8+ T cells were required for tumor protection in the vaccinated mice as determined by tumor growth kinetics." (PMID 22397502, 2012). "Studies have shown that several tumor-derived molecules are (CCL17, CC22, prostaglandin E2) involved in recruitment of CD4 Treg cells at tumor bed or periphery to induce tolerance against anti-tumor responses." (PMID 23152910, 2012). "During maturation DCs migrate from tumor tissues to T cell-rich areas of secondary lymphoid organs, where they activate tumor-reactive CD8+ CTLs and CD4+ T cells." (PMID 24213236, 2012). "This soluble SA-4-1BBL has shown potent immune activity as an adjuvant component of TAA-based vaccines by targeting various cells of innate, such as DCs and NK cells, and adaptive, such as CD4+ and CD8+ T cells, immunity in various preclinical tumor models." (PMID 23144888, 2012). "Immunohistochemically, the tumor cells were cytokeratin -, vimentin +, CD3+, CD45RO+, CD5-, CD7-, CD4-, CD8-, CD10-, CD20-, CD30-, CD79a-, CD138-, CD56-, granzyme B-, TIA-1 cytotoxic granule-associated RNA binding protein (TIA-1) + and ALK-." (PMID 22931631, 2012). "The tumor cells showed intense membrane staining for CD1a, strong granular cytoplasmic staining for langerin (CD207), strong staining for S100 and CD4." (PMID 23006414, 2012). "Although CD4+ cells play a role in mediating anti-GITR-induced immune activation against tumors, CD8+ cells are indispensable for tumor rejection." (PMID 22654588, 2012). "Frequencies of CD4+ and CD8+ T cells in tumor-infiltrating immune cells were 37% and 13% of the CD3+ population, respectively, and percentages of B and NK lymphocytes were even lower than percentages of CD3+ cells (1.2% for both CD19+ and CD56+ cells)." (PMID 23189169, 2012). "The lymphocytes that infiltrated the tumor tissue of the CCR5−/− mice also had higher levels of CD19, CD3, CD4, CD8 and CD57 when compared to the CCR5+/+ mice." (PMID 22567084, 2012). "Immunohistochemically, tumor cells showed CD3+, CD45RO+, CD5-, CD7-, CD4-, CD8-, CD10-, CD20-, CD30-, CD79a-, CD138-, CD56-, granzyme B-, TIA-1+ and ALK-." (PMID 22931631, 2012). "Immunohistochemistry was used to evaluate the CD3+, CD4+, CD8+ and CD20+ lymphocytes in the tumor and the peritumoral capsule." (PMID 22375962, 2012). "Ours and previously published data suggests that, like conventional CD4+ T cells and type II NKT cells, iNKT cells have the capacity to suppress anti-tumor immunity." (PMID 22880059, 2012). "Staining of intracellular cytokines demonstrated that CD3+CD4+ and CD3+CD8+ T cells in infiltrated IHL of the tumor adjacent liver tissues were the mainly IL17-producing cells." (PMID 23227158, 2012). "The majority of GFP+ tumor cells expressed CD48 (99.3±0.7%), CD47 (89.5±6.9%) and Mac1 (74.4±14.7%), while expression of Gr1 (4.73±2.65%), B220 (1.35±1.52%), CD4 (18.6±16.8%), and Ter119 (3.13±1.6%) was low or absent." (PMID 22952867, 2012). "In our study MELOE-1 derived specific CD4 T cell clones exhibited a high ratio IFN-γ/IL10, thus favourable to the development and the persistence of anti-tumour responses." (PMID 23284752, 2012). "Using a microglia/macrophage high gene signature derived from quantification of tumor-infiltrating cells in adult GBM, we identified enrichment of genes characteristic of CD4 T cells, granulocytes, and microglia/macrophages (n = 573)." (PMID 22937035, 2012). "Macrophage consists of the largest population of tumor infiltrating immune cells (3.45%), followed by NK cells (1.44%), CD8+ T cells (1.08%) and CD4+ T cells (0.23%)." (PMID 21264227, 2011). "In addition, this strategy may foster tumor-driven conversion of Treg from CD4+CD25−FoxP3− T cells." (PMID 22110524, 2011). "Tumor appeared in only 50–60% of the mice in MIP treated group and in these mice tumors were infiltrated with higher number of CD4+ and CD8+T cells, NK and NKT cells, macrophages and dendritic cells." (PMID 21984926, 2011).
tumor (continued). "PTCL is diagnosed when tumor cells express the mature T cell antigens CD2, CD3, CD4, CD5, CD6, or CD7 on immunohistochemical staining." (PMID 21310044, 2011). "4-1BB activation elicited strong infiltration of CD8+ T-cells into the tumor and drove the proliferation of these cells, while CTLA-4 blockade did the same for CD4+ effector T-cells." (PMID 21559358, 2011). "CD4 or CD8+ T cells expressing IFNγ, or the IFNγ inducing transcription factor Tbet, are the cells most likely involved at the tumour site." (PMID 21864372, 2011). "In mice treated with EGF-SEA, CD4+, CD8+ and SEA-reactive T lymphocytes were enriched around the EGFR expressing tumor cells." (PMID 21311755, 2011). "Our results showed that FoxP3+ Tregs highly aggregated and were in an activated phenotype (CD69+HLA-DRhigh) in the tumor site, where they can suppress the proliferation and INF-γ secretion of CD4+CD25− T cells." (PMID 21935436, 2011). "In addition, although some subsets of lymphocytes including cytotoxic CD8+ T cells and NK cells exhibit anti-tumor immunity, other subsets notably Th2 cells, CD4+ regulatory T cells and NKT cells may exhibit opposite effect on tumor progression by interfering with TAM properties." (PMID 21633700, 2011). "Accordingly, tumor infiltrating CD8+ and CD4+ T cells have been shown to have increased expression of PD-1 and are anergic." (PMID 24212948, 2011). "In this study, CD4+ T cells produced GM-CSF at significantly higher levels than TNF-α, IL-4, and IFN-γ in response to tumor lysates." (PMID 21931646, 2011). "Immunohistochemical analysis also revealed the infiltration of CD4+ T cells and CD8+ T cells into tumor tissue." (PMID 21649881, 2011). "α-TEA increased the frequencies of activated CD4+ and CD8+ T cells, resulted in higher CD4+-to-Treg and CD8+-to-Treg ratios in the tumor microenvironment and induced tumor-specific cytotoxicity." (PMID 21232138, 2011). "Infiltration of the skin with CD4+ T cells is a consequence of MDV infection and the high frequency tumor clones in the blood are likely to represent the relocation of MDV to the site of transmission." (PMID 21573129, 2011). "The relationship between CD4, CD8 or Foxp3 positive cells with clinico-pathological variables was examined (differentiation, lymphatic invasion, tumour margin, tumour site, vascular invasion)." (PMID 21864372, 2011). "Fourth, the SPIO DCs induced the proliferation of adoptively transferred CD4+ T cells but, most importantly, they primed cytotoxic CD8+ T cell responses to protect against a B16-Ova tumour challenge." (PMID 21637760, 2011). "CD4+CD25+ regulatory T cells (Tregs), a heterogeneous population, were enrichment in tumor mass and played an important role in modulating anti-tumor immunity." (PMID 21655250, 2011). "CD45+CD11c+ cells, including both CD11bhi and CD11bint DC subpopulations, were electronically sorted from tumor cell suspensions to a high purity (>96%) and used to stimulate the proliferation of OVA-specific CD4+ OTII and CD8+ OTI T cells in vitro." (PMID 21390236, 2011). "The internalized TAA are transported by APC to the regional lymph nodes, processed by these cells, and presented on MHC class I and class II molecules as TAA peptides that activate tumor-specific CD8+ cytotoxic T cells and CD4+ Th1 cells, respectively." (PMID 22162709, 2011). "In univariate analyses, increased numbers of CD4+ (P = 0.008) and CD20+ (P = 0.006) lymphocytes in tumor correlated significantly with an improved disease-specific survival (DSS) in patients with wide resection margins (n = 108)." (PMID 21298041, 2011). "It was observed that in MIP treated group, higher number of CD4+, and CD8+ T cells were infiltrating the tumor." (PMID 21984926, 2011). "The expansion of CD4+ T cells in lymphopenic hosts is accompanied by the production of IL-2, which is crucial in the regulation of CD4+CD25+ Treg cell homeostasis, anti-tumor CD8+ T cell responses and the generation of CD8+ T cell memory." (PMID 21423804, 2011).
tumor (continued). "We confirmed a significant enrichment of Foxp3-positive CD4 TIL and splenocytes in wild-type, B16 tumor-bearing C57BL/6 Foxp3EGFP mice." (PMID 22112546, 2011). "The density of both CD4(+) and CD8(+) T cells showed a strong correlation with the rate of decrease of tumor size evaluated by barium enema study (P = 0.0013, 0.0020)." (PMID 21575175, 2011). "Purified CD4+ T cells from C51-CIITA vaccinated and challenged mice were also efficacious in preventing tumor growth of C51 tumor, as 50% of the animals were protected and the remaining 50% displayed a significant growth retardation." (PMID 22110523, 2011). "The numbers of both CD4(+) and CD8(+) tumor-infiltrating lymphocytes (TIL) in pre-CRT biopsy samples were strongly correlated with tumor reduction ratio evaluated by barium enema." (PMID 21575175, 2011). "We assessed the capacity of predicted CD4 T-cell epitopes from STEAP and EZH2 to induce anti-tumor immune responses to LC cell lines." (PMID 22053850, 2011). "One such mechanism is represented by tumor-induced overexpression of CD80 (B7-1) on the surface of MDSCs, to which the inhibitory CTLA-4 (CD152) molecule expressed on CD4+CD25+ T cells binds with high affinity." (PMID 22190971, 2011). "The necessity of both T cell subsets for the α-TEA antitumor effect also correlated with the finding of higher frequencies of activated CD4+ and CD8+ T cells in the tumor microenvironment." (PMID 21232138, 2011). "At various tumor volumes, tumor-infiltrating lymphocytes (TIL), splenocytes (SPL), and lymph node (LN) cells were isolated and CD8 and CD4 T cells analyzed by flow cytometry for percentage expression of Foxp3 (EGFP)." (PMID 22112546, 2011). "Immunohistochemical staining showed that CD4-positive T cells were detected in all grades of OSCC and that the CD4+ cells were predominantly observed in tumor stroma." (PMID 24213108, 2011). "Sometimes, this CD8 T cell response is triggered independently of the presence of a tumor specific CD4 T cell response whereas in other cases the CD4 and CD8 T cells can act separately in tumor rejection as in the case of VLPs." (PMID 21918683, 2011). "Finally, there is evidence to suggest that the GBM microenvironment may divert CD4+ T cell differentiation away from a tumor-directed cytotoxic Th1-mediated response and toward a Th17-mediated chronic inflammatory response, which has been shown to be protumorigenic in other cancers." (PMID 22190972, 2011). "More recently it has been reported that antigen-specific CD4 helper T cells can enhance recruitment of CD8 T cells to tumors, and overcome the immunosuppressive tumor microenvironment." (PMID 22046294, 2011). "Both CD4+ and CD8+ T cells were required for tumor growth inhibition to occur in mice injected intratumorally with CCL21." (PMID 21450101, 2011). "Since the tumors are derived from CD4+ T cells, the clonally expressed T cell receptor (TCR) would be an appropriate target for the molecular definition of tumor clonality." (PMID 21573129, 2011). "The APC process and present immunogenic TAA peptides and thus, effectively activate tumor specific CD4+ helper T cells and CD8+ cytotoxic T cells which destroy tumor cells in micrometastases." (PMID 22162709, 2011). "Once the tumor formed a site for the retention of EGF-SEA proteins, it was possible for tumor-unspecific T lymphocytes including CD4+ and CD8+ T cells to be likewise retained." (PMID 21311755, 2011). "Although Tim-3 and PD-1 can negatively regulate both CD4+ Th1 and CD8+ T cells, under various chronic infection or tumor-bearing conditions, the frequency of antigen-specific CD8+ T cells positive for both TIM-3 and PD-1 is the highest." (PMID 22168579, 2011). "Several publications report on a decrease in regulatory T cells in spleens and lymph nodes (defined as CD4+ CD25+ cells) and subsequent enhancement of the anti-tumor response when including cyclophosphamide in an immunotherapeutic strategy." (PMID 21859450, 2011).
tumor (continued). "4-1BB agonist antibody treatment induced widespread expression of the molecule killer cell lectin-like receptor subfamily G member 1 (KLRG1) as well as the co-inhibitory receptor programmed death 1 (PD-1) on tumor-infiltrating CD8+ and CD4+ effector T-cells." (PMID 21559358, 2011). "We investigated the effects of depleting CD4+CD25+ “natural” regulatory T cells (Treg) on the frequency, phenotype and function of total dendritic cell populations in B16.OVA tumors and in tumor-draining lymph nodes." (PMID 21390236, 2011). "We observed that this approach (LRAST) increases the systemic anti-tumor immune response and initially reduces the number of FoxP3+CD25+CD4+ Tregs." (PMID 21859450, 2011). "Indicative of the central role of CD4+ T-cells with this vaccine, adoptive transfer of sera containing VEGF antibodies blocked tumor growth and angiogenesis in vivo." (PMID 21385454, 2011). "A study has revealed that in parallel to high levels of CD4+Foxp3+ Treg cells, IL-17+ T cells including CD4+ T cells and CD8+ T cells were kinetically induced in the tumor microenvironment in multiple mouse and human tumors." (PMID 21943203, 2011). "At various tumor volumes, SPL, LN, and TIL were analyzed for percent expression of Foxp3EGFP in CD8 and CD4 T cells." (PMID 22112546, 2011). "In 48 cases of advanced RC, we retrospectively examined the density of tumor infiltrating CD4(+) and CD8(+) T cells using immunohistochemical staining of biopsy samples before CRT, and examined the correlation with tumor response." (PMID 21575175, 2011). "Strategies have been developed to use patient's T cells (CD4+ and CD8+) and IgGs for the identification and characterization of tumor antigens." (PMID 24212823, 2011). "Based on depletion of CD4+ and CD8+ T-cell experiments, the anti-angiogenic and anti-tumor action of the vaccine was primarily the result of CD8+ T-cells." (PMID 21385454, 2011). "In order to elucidate the contribution of CD4+ and CD8+ T cells towards tumor cell recognition, we negatively separated the Fc1-stimulated T cells magnetically to high purity." (PMID 21943054, 2011). "An increase of CD4+CD25+Foxp3+ Tregs has been observed in the peripheral blood and in the tumor site of patients with nasopharyngeal carcinoma." (PMID 21437225, 2010). "CD4+ and CD8+ cells were depleted separately or together using i.p. injections of anti-CD4 and anti-CD8 mAbs starting two days before tumour cell challenge, and thereafter every 4–5 days." (PMID 20657846, 2010). "Tumor cell recognition by HCV TCR transduced CD8− Jurkat cells and CD4+ PBL-derived T cells indicated this TCR was CD8-independent, a property consistent with other high affinity TCRs." (PMID 20686664, 2010). "Single depletion of CD4+, CD8+ or NK cells still resulted in a statistically significant anti-tumour response compared to unimmunized mice." (PMID 20657846, 2010). "The virus antigens expressed in the tumor cell are neo-antigens recognized by host immune cells, so many different lymphocytes are homing to tumor tissues including CD8+ T cells, CD4+ T cells and other immune cells." (PMID 20064222, 2010). "Immunohistochemical quantification (score 0-3) was performed for CD3, CD4, CD8, CD45RO, CD68, CD163, FoxP3, GranzymeB, iNOS, mast cell tryptase, MUM1, PD1 and TIA-1 tumor-infiltrating (TILs) reactive cells." (PMID 21179245, 2010). "As a complement to the depletion of different subsets of immune cells in normal BALB/c mice, tumour rejection experiments were also performed in CD4−/− single, CD8−/− single, or CD4−/−CD8−/− double knock-out C57Bl/6 mice." (PMID 20657846, 2010). "When manipulating the system by depletion of CD4+ and/or CD8+ cells, it was easier to obtain an abrogation of the anti-tumour response compared to the BALB/c model." (PMID 20657846, 2010). "Tumour takes after depletion of CD4+ cells, CD8+ cells and/or NK cells in the effector phase in BALB/c and C57Bl/6 mice, respectively, as well as tumour takes in C57Bl/6 knock-out mice." (PMID 20657846, 2010).